USP17L19 (ubiquitin specific peptidase 17 like family member 19)
Description:
Deubiquitinating enzyme that removes conjugated ubiquitin from specific proteins to regulate different cellular processes that may include cell proliferation, progression through the cell cycle, apoptosis, cell migration, and the cellular response to viral infection.
Tractability: No criterion of Open Targets' tractability assessment is met for any kind of drug.
Gene: Protein-coding gene on chromosome 4 (9,253,378 to 9,254,970, forward strand). Ensembl gene ENSG00000248920.
Subcellular location: Nucleus; Endoplasmic reticulum
Pathways (Reactome):
Metabolism of proteins: Ub-specific processing proteases
Gene Ontology:
Molecular function: cysteine-type deubiquitinase activity
Biological process: regulation of apoptotic process; protein deubiquitination
Cellular component: endoplasmic reticulum; nucleus
Homologues: Paralogues in human: USP17L11 (99% identical), USP17L22 (99% identical), USP17L18 (99% identical), USP17L20 (99% identical), USP17L12 (99% identical), USP17L17 (99% identical), USP17L24 (99% identical), USP17L25 (99% identical), USP17L26 (99% identical), USP17L27 (99% identical), USP17L28 (99% identical), USP17L29 (99% identical), and 59 more.